AHR (aryl hydrocarbon receptor)
Diseases named in the same sentence as AHR in open-access papers (continued):
Sharing a sentence is not in itself a finding about the gene and the disease.
inflammation (31 papers, 2011 to 2025). Aberrant reaction of the microcirculation characterized by movement of fluid and leukocytes from the blood into extravascular tissues. "In models of hyperoxic lung injury in adult animals, AHR deficiency potentiates hyperoxia-induced lung inflammation and damage, whereas AHR activation mitigates these effects of hyperoxia." (PMID 35163440, 2022). "Importantly, the Pb-induced lung inflammation and apoptosis were associated with a proportional increase in the expression of NF-κB and AhR mRNAs and proteins." (PMID 35482242, 2022). "Since ITGB4 deficiency caused spontaneously pulmonary inflammation and AHR after birth, we further detected whether ITGB4 deficiency influenced pulmonary inflammation and AHR after exposure to HDM in the postnatal period." (PMID 31970850, 2020). "Collectively, several studies have demonstrated that the induction of AhR signaling has the capacity to attenuate autoimmune CNS inflammation, suggesting that AhR is an important therapeutic target that exemplifies the complexity of gut–brain interactions." (PMID 38534341, 2024). "In a mouse study using DSS-induced intestinal inflammation it was shown that the activation of AhR by FICZ, a high-affinity ligand for AhR, led to reduced severity of mucosal inflammation in mice compared with control subjects." (PMID 39461590, 2024). "These tryptophan-derived microbial metabolites are endogenous ligands for aryl hydrocarbon receptor (AhR), which can trigger renal inflammation and fibrosis." (PMID 37375602, 2023). "Especially, cockroach allergen–treated AhR−/− mice showed exacerbation of airway inflammation when compared with WT mice, which was further supported by using an AhR agonist 2,3,7,8-tetrachlorodibenzo-p-dioxin (TCDD)." (PMID 35935956, 2022). "In chronic ozone exposure-induced airway inflammation and hyperreactivity, recruitment of IL-22-producing cells including ILC3s, NK cells, and T cells was modulated by AhR, resulting in the inflammation control." (PMID 33718260, 2021). "Similar to the findings in helminthic lung infections, ST2+ nILC2s (called ILC217s) are defined in the lung inflammation induced by papain or IL-33, which possesses some characteristics of ILC3s, for example, AhR expression and IL-17 production." (PMID 33718260, 2021). "We have shown that single or repeated exposure of ZnONPs induces pulmonary inflammation, accompanied by an activated AhR pathway in the bronchial and bronchiolar epithelial cells and macrophages in the mouse lungs." (PMID 32414036, 2020). "To explore the further pathogenesis of PM2.5-induced airway inflammation, we focused on the role of AhR in the pathology process." (PMID 29959403, 2018). "Our results show that EPFR-containing DCB230 induced dramatic and sustained AHR and pulmonary inflammation in neonatal rats." (PMID 21388553, 2011). "Using ABX-treated mice, we showed that gut-dysbiotic mice developed uterine inflammation and endometrial barrier function damage, which are consistent with AhR activation impairment in the uterus and may be due to the abrogation of the intestinal microbiota." (PMID 35727038, 2022). "Given the significance of autophagy in AT2 cell AhR-modulated allergic airway inflammation, we asked whether inhibition of autophagy can suppress cockroach allergen–induced airway inflammation by using autophagy inhibitor CLQ in our mouse model following the protocol illustrated in." (PMID 35935956, 2022). "Deficient AHR signaling has been reported to affect immune and non-immune cells, such as neutrophils, macrophages, and fibroblasts in the lung, leading to increased lung inflammation upon exposure to tobacco smoke, lipopolysaccharide, and hyperoxia." (PMID 35163440, 2022).
inflammation (continued). "Therefore, AhR ligands (e.g., dietary substances, tryptophan photoproducts, and environmental pollutants) have the potential to be involved both as tools for comprehending the role of the AhR in lung inflammation and as therapeutics for the treatment of various inflammatory lung diseases." (PMID 29670460, 2018). "In conclusion, we demonstrate that AHR activation by indolic uremic toxins disrupts TAK1-related TGFβ signaling, inducing endothelial inflammation through overexpression of IL-8 and MCP-1 chemokines." (PMID 41003499, 2025). "One study showed that adult rat progeny born to dams exposed to TCDD developed hypertension, which is related to the activation of AhR signaling and induction of TH17-dependent renal inflammation." (PMID 37375602, 2023). "We reported previously that ZnONPs-induced pulmonary inflammation is mediated through inflammatory cytokine–indoleamine 2,3-dioxygenase (IDO1)–aryl hydrocarbon receptor (AhR) loop in the lung macrophages and epithelial cells." (PMID 32414036, 2020). "On the other hand, PAHs, through activation of the Aromatic Hydrocarbon Receptor (AhR), inhibit T cell differentiation, reduce interferon-γ (IFN-γ) secretion, and induce a Th17-type inflammatory response, exacerbating lung inflammation but reducing protective immunity." (PMID 41256266, 2025). "Not only do our data confirm the importance of AhR activation in suppressing airway inflammation but we also show using novel lineages of mice incapable of nuclear AhR localization or DRE binding, that a novel AhR pathway confers protection against smoke-induced lung inflammation." (PMID 33659010, 2021). "In the present study, we demonstrate that TCDD-induced AhR activation reduced non-eosinophilic airway inflammation via the inhibition of Th17 differentiation and IL-17 expression and the promotion of Treg differentiation and IL-10 production." (PMID 26938767, 2016). "In conclusion, our study demonstrates that TCDD-induced AhR activation inhibits the development of non-eosinophilic airway inflammation by regulating the differentiation of Th17 and Tregs." (PMID 26938767, 2016). "Finally, we investigated the effect of TCDD-induced AhR activation on DC maturation in non-eosinophilic airway inflammation." (PMID 26938767, 2016). "AhR activation plays an important role in the regulation of the immune system; thus, we subsequently investigated whether TCDD-induced AhR activation was involved in T cell differentiation in non-eosinophilic airway inflammation." (PMID 26938767, 2016). "Thus, TCDD-induced AhR activation alleviates non-eosinophilic airway inflammation potentially via the inhibition of both Th2-type and Th17-type immune responses." (PMID 26938767, 2016). "Thus, we subsequently investigated whether TCDD-induced AhR activation has an impact on Th17 cytokine expression in non-eosinophilic airway inflammation." (PMID 26938767, 2016). "In conclusion, we demonstrated that indolic uremic toxins promote endothelial inflammation by inducing IL-8 and MCP-1 expression via AHR activation and non-canonical TGF-β signaling." (PMID 41003499, 2025). "Our findings demonstrate that the absence of PARP7 protein results in an impaired immune response to colonic inflammation and suggests that PARP7 may participate in the recruitment of immune cells to the inflammation site, which may be due to its role in IFN-I signaling rather than AHR signaling." (PMID 35055106, 2022).
kidney disease (22 papers, 2019 to 2025). "Aberrant AhR signaling, especially due to maternal exposure to exogenous ligands, has been linked to developmental programming of disease, including kidney disorders." (PMID 41154514, 2025). "Our study will uncover that BSA ameliorate podocyte damage-associated renal disease by improving IƙB/NF-ƙB and Keap1/Nrf2 pathways via suppressing hyperactive AHR expression." (PMID 39239643, 2024). "Previous study has suggested that hyperactive AHR signal was implicated in patients with podocyte damage-associated renal disease such as immunoglobulin A nephropathy (IgAN), diabetic kidney disease (DKD) and idiopathic membranous nephropathy (IMN)." (PMID 39239643, 2024). "Taken together, these results show that upregulated AhR activity in the kidney may be associated with the high IS level in renal disease." (PMID 31488157, 2019). "Emerging evidence suggests that AhR-induced oxidative stress is a key contributor to kidney disease." (PMID 41154514, 2025). "Increasing evidence shows that hyperactive aryl hydrocarbon receptor (AHR) signalling is involved in renal disease." (PMID 39239643, 2024). "Targeting AhR with agonists or antagonists has shown promising initial efficacy in various kidney disease models." (PMID 38491448, 2024). "Published reports have shown therapeutic benefits of suppressing the mTOR and AhR signaling pathways in the treatment of kidney diseases, including DN." (PMID 39902076, 2024). "Considering the double-edged sword effects of AhR in kidney diseases, the selection of AhR agonists or antagonists should be cautious and confirmed in experimental and clinical studies." (PMID 38491448, 2024). "A distinct time-dependent and tissue-specific AhR activation is displayed in different mouse models of kidney diseases." (PMID 36635272, 2023). "It is clear AhR plays an important role in the pathology of cardiovascular and renal disease in the setting of CKD, offering a new possibility for therapeutic intervention." (PMID 35202128, 2022). "This calls for further exploration to fully elucidate the role of NPTX1 both in the AhR pathway and in renal disease." (PMID 35216489, 2022). "A positive correlation between the increased activation of AhR signaling and CKD has also been shown, suggesting the deleterious effect of AhR signaling in kidney disease." (PMID 31382511, 2019). "However, AhR is still an intriguing and valuable therapeutic target for kidney diseases because of its important effect on renal injury and associated complications and response to uremic toxins." (PMID 38491448, 2024). "When renal function is impaired, the accumulation of uremic toxins accelerates the progression of kidney diseases by activating the AhR signaling pathway, and this damage occurs not only in the kidney but also in other organs, such as the heart, vessel, liver and muscle." (PMID 38491448, 2024). "AHR (aryl hydrocarbon receptor) is another gene that has been implicated in kidney disease, although its role is not as extensively studied yet." (PMID 37510393, 2023). "Few studies have demonstrated whether AhR can interact with these signalling pathways in kidney disease." (PMID 31488157, 2019). "Although targeting uremic toxins and the AhR pathway are promising approaches, further elucidation of AhR regulation and investigations into the effects of specific agonists/antagonists are required to develop optimal therapies for human kidney disease treatment." (PMID 38491448, 2024). "Contrary to NPHS2 and AHR, which is a well-known gene involved in kidney function, the role of CHCHD4 in kidney disease has not been studied as much." (PMID 37510393, 2023).
immune diseases (20 papers, 2006 to 2026). "The current literature separately describes the role of AhR in MC signaling, as well as the contributions of MCs to liver pathology and the disrupted gut-liver axis, which drives immune dysfunction in chronic liver disease." (PMID 41827882, 2026). "Studies have shown that AhR activity can play an important role in controlling the severity of immune diseases, especially in mouse models of lupus." (PMID 40264032, 2025). "Interventions that affect AhR can impact the outcome of immune diseases, making AhR a potential target for immunotherapy." (PMID 39904603, 2025). "Indole compounds and their derivatives are ligands of AHR, which can activate the AHR signal transduction pathway and show significant regulatory potential in various inflammatory and immune diseases." (PMID 41155173, 2025). "These diverse roles highlight AhR’s dynamic impact on immune regulation and underscore its great potential as a therapeutic target for neuro-immune disorders." (PMID 39211042, 2024). "We have demonstrated that KYNU and the requirement for tryptophan via WARS, association of the transcriptional activators AHR and HCAR3, along with ADPR and PARP1, are sufficient drivers for persistent immune disease." (PMID 36499104, 2022). "Aryl hydrocarbon receptor (AhR), a ligand-activated transcription factor, has been considered as an important regulator for immune diseases." (PMID 35935956, 2022). "Identification of alternative AhR agonists is a critical step in evaluating the AhR as a therapeutic target for the treatment of immune disorders." (PMID 20957046, 2010). "Activation of the AhR by dioxins results in the induction of xenobiotic metabolism and successive toxic responses, including hepatocellular damage, immune system disorders, reproductive system disorders, teratogenesis and carcinogenesis." (PMID 16956419, 2006). "Furthermore, the use of AHR agonists or antagonists may influence the outcomes of infectious and immune diseases, highlighting AHR as a potential target for immunotherapy." (PMID 39575260, 2024). "AhR is a negative regulator of IL17-mediated signal transduction and plays an important role in resisting pathogens of immune diseases." (PMID 36601073, 2022). "The growing understanding of the function of AHR in various diseases, in addition to ophthalmic diseases, is fueling attempts to target AHR in the treatment of diseases, including AMD, certain tumors, immune disorders and inflammatory diseases." (PMID 34698116, 2021).
bacterial infection (19 papers, 2017 to 2025). "Studies have demonstrated that AHR-deficient mice are more susceptible to bacterial infection than wild-type mice." (PMID 37179416, 2023). "Loss of AHR in endothelia exacerbates lung damage and promotes infiltration of red blood cells and leukocytes into alveolar air spaces, compromises barrier protection, and increases host susceptibility to secondary bacterial infections." (PMID 37587341, 2023). "AHR-deficient mice are more susceptible to viral and bacterial diseases." (PMID 34559251, 2021). "AhR plays a key role in host defense mechanisms against both extracellular and intracellular bacterial infections." (PMID 39767818, 2024). "In this study, KLF10 was identified as a major transcription factor downstream of AhR in response to a bacterial infection in mosquitoes." (PMID 35397616, 2022). "The reason for the higher mortality rate of mice lacking AhR seems to be a hypersensitivity to LPS-induced septic shock, supporting the crucial role of AhR for a balanced systemic immune response to bacterial infection." (PMID 35203386, 2022). "This study focused on immunomodulatory effects of aryl hydrocarbon receptor (AhR) activation through benzo[a]pyrene (BaP) during systemic bacterial infection." (PMID 35203386, 2022). "To identify genes that are regulated by AhR upon the bacterial infection, we conducted RNA sequencing (RNA-seq) to profile the transcriptomes upon treatment." (PMID 35397616, 2022). "For instance, proper wound healing and defense against bacterial infections are controlled by AhR-dependent IL-22 secretion from innate and adaptive cells." (PMID 36601108, 2022). "For example, AHR agonists in the gastrointestinal tract appear to enhance barrier function in part through enhanced IL22 expression, which in turn helps protect the gut from pathogenic bacterial infection and genotoxic stress." (PMID 40077746, 2025). "Finally, one of ways through which the AhR contributes to the defense against bacterial infection is by sensing bacterial products (i.e., virulence factors) from Pseudomonas aeruginosa [P." (PMID 30563036, 2018). "Also, AHR is essential for defense against acute and chronic bacterial infections." (PMID 37179416, 2023). "Taken together, there is sufficient evidence to speculate that the AhR may lessen the susceptibility to COPD pathogenesis by attenuating CS-induced pulmonary inflammation, oxidative stress, lung structural cell loss and bacterial infections that can trigger exacerbations." (PMID 30563036, 2018). "Consequently, AhR-deficient mice or mice fed a AhR-ligand deficient diet failed to clear intestinal bacterial infections." (PMID 29375541, 2017). "In this study, we demonstrate that mosquito AhR and KLF10 mediate a transcriptional axis that directs a transcriptional regulatory network in the immune context using a bacterial infection model." (PMID 35397616, 2022). "In the inflammatory environment during a viral or some bacterial infections, IFNγ is secreted by immune cells leading to significant expression of IDO that in turn metabolizes tryptophan to kynurenine, which is a weak AHR agonist." (PMID 33348604, 2020). "The human aryl hydrocarbon receptor (AhR), a protein well-known for its function in mediating toxicity, has been shown to interact with several QS molecules (such as 3-oxo-C12-HSL, C4-HSL, and PQS) produced by P. aeruginosa to keep track of the bacterial infection at various stages." (PMID 36835135, 2023). "DAAO catalyzes the production of AHR agonists, including indole-3-pyruvic acid (I3P) though the enzymatic conversion of D-tryptophan to I3P, and is found in neutrophils which produce MPO and hypochlorous acid with immediate effect on the resilience to bacterial infection noted." (PMID 36499104, 2022). "High AhR expression in the placenta and/or fetal membranes may result in myometrial contractions by hyperactivation of the cytokines/COX2/PGs pathway either directly or in synergy with bacterial infection." (PMID 34360926, 2021).
dermatitis (18 papers, 2016 to 2026). An inflammatory process affecting the skin. "The current study suggests that KF exerts therapeutic effects on skin disorders by increasing AhR and Nrf2 activity, as observed in HaCaT cells and an AD mouse model." (PMID 41229709, 2025). "Actually, it has been reported that, while blocking AhR activation is desirable in some skin conditions, stimulating this activation is beneficial in another group of skin disorders." (PMID 37373144, 2023). "Firefighters’ regular dermal exposure to PAHs promotes the development and/or aggravation of skin disorders, with limited evidence suggesting increased values of AhR-mediated toxicity and urinary PAH metabolites after participation in fires." (PMID 36231977, 2022). "There are several ways to demonstrate that AhR is a key regulator of skin disorders." (PMID 36983027, 2023). "Our findings show that AS-IV induces melanogenesis through AhR-dependent AKT/GSK-3β/β-catenin pathway activation and could be beneficial in the therapy for depigmented skin disorders." (PMID 33381211, 2020).